GSN (gelsolin)
Diseases named in the same sentence as GSN in open-access papers (continued):
Sharing a sentence is not in itself a finding about the gene and the disease.
glioma (10 papers, 2012 to 2025). A benign or malignant brain and spinal cord tumor that arises from glial cells (astrocytes, oligodendrocytes, ependymal cells). "The results of survival analysis show that the high GSN expression associated with poorer prognosis in glioma and GBM patients." (PMID 38803199, 2024). "For example, histone acetylation suppresses human glioma cell proliferation by enhancing the expression of p21 and gelsolin." (PMID 39845013, 2025). "Consistent with the result in glioma, the higher GSN expression exhibited a significantly shorter survival than lower GSN expression in recurrent glioma and GBM." (PMID 38803199, 2024). "Our data revealed that overexpression of the GSN appears significantly correlated with unfavourable OS in glioma." (PMID 38803199, 2024). "Through RNA sequencing data analysis, we evaluated the relationship between GSN expression levels, IDH mutations, and MGMT methylation status in glioma obtained from the CGGA database." (PMID 38803199, 2024). "GSN and HP are proteins present in plasma, but they also play a role in meningiomas and gliomas, where GSN is downregulated." (PMID 37627098, 2023). "High expression of GSN was enriched in malignant phenotype of glioma." (PMID 38803199, 2024). "In this context, it is interesting to mention that in a reported case of pituicytoma, a very rare glioma of the pituitary gland of unknown cell origin, there were observed gelsolin amyloid deposits." (PMID 25352156, 2016). "In the BrM/Glioma group, 8 DEPs (PRL, SNCA, MACF1, ACAT2, VWF, GSN, FCGBP, and F10) were selected for ROC curve analysis based on a logistic regression model." (PMID 39716938, 2025). "GSN is a biomarker candidate for GBM and inhibits glioma proliferation and invasion." (PMID 36291348, 2022). "On the other hand, mTORC2 were not strongly interacting with GSN, MYH9, as well as AKT, a known mTORC2 substrate, in low-grade glioma cell lines." (PMID 37120454, 2023).
heart failure (10 papers, 2013 to 2025). Inability of the heart to pump blood at an adequate rate to meet tissue metabolic requirements. "The gelsolin-driven actin cytoskeletal remodelling (depolymerisation) in heart failure was mechanistically underlined by increased expression of atrial and beta natriuretic peptides and increased cross-sectional areas of cardiomyocytes and chamber dilation." (PMID 35900667, 2023). "Here the authors show that gelsolin is negatively regulated in the heart by PI3Kα‐ generated PIP3, and that loss of gelsolin activity prevents adverse cytoskeletal remodeling and heart failure." (PMID 30568254, 2018). "Consistent to the upper chamber of the heart, PI3Kα-dominant negative mutant mice with heart failure pressure overload had dilated cardiomyopathy, by increased gelsolin-mediated actin severing activities in vivo." (PMID 35900667, 2023). "Much experimental evidence indicates a crucial role of GSN-mediated actin remodeling during heart remodeling in the pathogenesis of heart failure." (PMID 34685680, 2021). "Consistent with this, pressure-overload stimulated the severing of cytoskeletal actin filaments by gelsolin in mouse cardiomyocytes, in contrast, in gelsolin KO mice aberrant cytoskeletal remodeling, and heart failure was prevented." (PMID 33303625, 2021). "PI3Kα also negatively regulates gelsolin-activity to suppress gelsolin’s actin-severing activity that contributes to cardiac remodelling in heart failure." (PMID 32002690, 2020). "Our data identify the role of gelsolin-driven cytoskeletal remodeling in heart failure in which PI3Kα/PIP3 act as negative regulators of gelsolin activity." (PMID 30568254, 2018). "Deletion of gelsolin prevents biomechanical stress-induced adverse cytoskeletal remodeling and heart failure in mice." (PMID 30568254, 2018). "A previous study has showed that gelsolin is an important contributor to heart failure progression through novel mechanisms of HIF-1α and DNase I activation and downregulation of antiapoptotic survival factors." (PMID 23533533, 2013). "As several genes (MB, DJ-1, and GSN) identified via quantitative proteomics are also involved in heart failure following MI18, 19, 20, we examined whether WE intake could modulate pathological LV remodelling after MI." (PMID 27929093, 2016).
cervical carcinoma (9 papers, 2009 to 2024). A carcinoma arising from either the exocervical squamous epithelium or the endocervical glandular epithelium. "Our results support this, as GSN knockdown promoted the metastasis, growth and glycolysis of cancer cells and low levels of GSN expression were associated with poor prognosis in cervical cancer patients." (PMID 35941115, 2022). "Taken together, our results demonstrate that elevated expression of methylated HBP1 and reduced levels of GSN in cervical cancer are associated with poorer prognosis." (PMID 35941115, 2022). "In biological network analysis, a closed protein interaction was found between GSN and the oncogene NF-κB in cervical cancer." (PMID 37958747, 2023). "Cervical cancer patients expressing gelsolin had a decreased 5-year survival rate in comparison to those not expressing gelsolin." (PMID 26356073, 2015). "Decreased gelsolin expression caused decreased cell migration, MMP2 expression, vimentin, and upregulated E-cadherin expression in cervical cancer cells." (PMID 26356073, 2015). "Of the 17 downregulated proteins, 6 different proteins showed low expression in both vaginal and cervical carcinoma compared with normal vaginal tissue (calreticulin, tropomyosin 2 beta, vimentin, gelsolin, vinculin and filamin)." (PMID 19367286, 2009). "Upregulated UHRF1 silences GSN to suppress the death of early cervical cancer cells in CESC." (PMID 37035750, 2023). "Gelsolin is an actin-binding protein that is upregulated in cervical cancer cells." (PMID 26356073, 2015). "For gelsolin, a direct interaction with HPV-E7 has been demonstrated to exert anti-apoptotic and pro-survival effects and to be critical for cell movement and invasiveness in cervix carcinoma." (PMID 32545200, 2020).
familial amyloidosis of Finnish type (9 papers, 2015 to 2026). "Familial Amyloidosis of Finnish type (FAF) is a rare autosomal dominant hereditary amyloidosis associated with genetic variants of gelsolin." (PMID 42232968, 2026). "Multiple mutations within the PrLD of the gelsolin protein (derived from the GSN gene) are associated with Finnish type familial amyloidosis [also referred to as Meretoja syndrome;] and are predicted to increase aggregation propensity." (PMID 31914925, 2020). "She had severe bilateral facial paresis, significant orbicularis, and perioral sagging as well as hypoesthesia of extremities and was diagnosed with Meretoja's syndrome at the age of 50, confirmed by the presence of gelsolin mutation." (PMID 28250773, 2017). "Gelsolin amyloidosis is a relatively rare genetic disease caused by accumulation of aggregated proteolytic fragments of the protein gelsolin." (PMID 27633054, 2016). "Gelsolin amyloidosis is a rare autosomal dominant genetic disease, which typically affects the cornea, skin and sometimes other organ systems and is caused by mutations in a gene coding for gelsolin protein (GSN)." (PMID 33499149, 2021). "Gelsolin amyloidosis (AGel) is characterized by multiple systemic and ophthalmic features resulting from pathological tissue deposition of the gelsolin (GSN) protein." (PMID 36430461, 2022). "Gelsolin amyloidosis (also known as AGel, familial amyloidosis of Finnish type or Meretoja syndrome) is a form of autosomal dominant systemic amyloidosis associated with pathogenic mutations in the GSN gene, encoding the multidomain protein gelsolin." (PMID 33499149, 2021).
AGel amyloidosis (8 papers, 2014 to 2026). "Hereditary gelsolin amyloidosis (AGel) is a rare and often underrecognized protein misfolding disorder caused by mutations in the gelsolin (GSN) protein, leading to its aggregation in various tissues." (PMID 41832348, 2026). "Gelsolin amyloidosis (AGel amyloidosis) is a hereditary systemic amyloidosis in which, a point mutation in the gelsolin gene leads to the formation of aggregating fragments of plasma gelsolin." (PMID 38944121, 2024). "Gelsolin amyloidosis (AGel amyloidosis) is a hereditary systemic protein misfolding disease that is caused by mutations in the gelsolin gene." (PMID 37590229, 2023). "AGel amyloidosis is caused either by the point mutation c.640G > A in the gelsolin gene on chromosome 9 at q33.2 or, less frequently, by the mutation c.640G > T at the same locus." (PMID 31952544, 2020). "Hereditary gelsolin amyloidosis (AGel amyloidosis) is an autosomal dominant form of systemic amyloidosis, caused by a c.640G>A or c.640G>T (earlier known as G654A or G654T) gelsolin gene mutation." (PMID 25097823, 2014). "Hereditary gelsolin amyloidosis (AGel amyloidosis) is an autosomal dominant form of systemic amyloidosis caused by a c.640G>A or c.640G>T mutation in the gene coding for gelsolin." (PMID 25097823, 2014). "The symptoms of AGel amyloidosis are suggested to be based on the deposition of gelsolin-based amyloid (AGel) fibrils and pre-amyloid oligomers, originating from misfolded gelsolin fragments and accumulating in multiple organs and tissues." (PMID 31952544, 2020). "AGel amyloidosis is a genetic degenerative disease characterized by the deposition of insoluble gelsolin protein aggregates in different tissues." (PMID 29069428, 2018).
oral cancers (8 papers, 2015 to 2022). "GSN over expression has been associated with the progression of oral carcinoma." (PMID 32664456, 2020). "The previous study reported that the GSN protein levels are lower in some human cancer cells, including breast, bladder, gastric, lung, and oral cancers, relative to healthy controls." (PMID 35941115, 2022). "During the progression of carcinogenesis, biphasic expression of GSN was found in oral cancers." (PMID 35205837, 2022). "In oral cancer cell line, upregulation of gelsolin promoted cell growth and motility, indicating that it may perform a vital function in the progression of oral cancer." (PMID 33171868, 2020). "Moreover, GSN overexpression is considered a poor prognostic factor in patients of oral cancer and non-small cell lung cancer." (PMID 29513714, 2018). "In oral cancers, biphasic expression of GSN was found during the progression of carcinogenesis." (PMID 26482896, 2015).
glioblastoma (7 papers, 2008 to 2025). The most malignant astrocytic tumor (WHO grade IV). "However, overexpression of GSN in bladder cancer and glioblastoma (GBM) cells leads to a loss of tumorigenicity." (PMID 35941115, 2022). "Furthermore, upregulated GSN may suppress cancer cell proliferation and metastasis for glioblastoma and myelodysplastic syndrome (MDS)." (PMID 37035750, 2023). "Similar results were obtained with human glioblastoma cells (NCH149) infected with H1-PV, indicating that dependence on gelsolin is a general, late feature of PV infection." (PMID 18704167, 2008).
non-small cell lung carcinoma (7 papers, 2006 to 2023). A group of at least three distinct histological types of lung cancer, including non-small cell squamous cell carcinoma, adenocarcinoma, and large cell carcinoma. "A similar result has been reported in non-small cell lung carcinoma, where a high gelsolin expression was associated with increased tumor grade." (PMID 34144901, 2022). "There are few reports on survival outcomes associated with GSN overexpression, although poor survival was reported in non-small cell lung cancer and osteosarcoma." (PMID 30148861, 2018). "In addition, it has been shown that upregulated expression of the GSN promotes radioresistance in non-small cell lung cancer cells and inhibits radiation-induced apoptosis through activation of PI3K/Akt signaling." (PMID 37958747, 2023). "Although MCM2, Ki-67, two markers of cell proliferation, and gelsolin, marker of cell motility, have been previously studied, no study has been conducted assessing the potential combined prognostic effect of these markers in non-small cell lung cancer (NSCLC)." (PMID 16882345, 2006).
acute respiratory distress syndrome (6 papers, 2010 to 2024). Progressive and life-threatening pulmonary distress in the absence of an underlying pulmonary condition, usually following major trauma or surgery. "In every acute tissue injury setting examined, including toxic, hyperoxic, and idiopathic lung injury, adult respiratory distress syndrome, acute liver injury, myonecrosis, pancreatitis, trauma, burns and bacterial and protozoal sepsis, plasma gelsolin levels are subnormal." (PMID 23880145, 2013).
gynecological cancers (6 papers, 2015 to 2024). "The expression of the actin-associated protein cytosolic gelsolin (GSN) regulates the gynecological cancer cell fate resulting in dysregulation in chemosensitivity." (PMID 31700155, 2020). "Furthermore, chemo-resistant gynecological cancer cells demonstrate elevated levels of gelsolin expression, and its overexpression correlates with the aggressive behavior exhibited by gynecological cancer cells." (PMID 39000458, 2024). "Recent studies have found increased GSN expressions in chemoresistant head-and-neck (HNC) and gynecological cancers." (PMID 35205837, 2022). "Recent studies have found the increased GSN expressions in chemo-resistant head and-neck (HNC) and gynecological cancers." (PMID 26482896, 2015).
head and neck cancer (6 papers, 2019 to 2023). A primary or metastatic malignant neoplasm affecting the head and neck. "GSN is also associated with chemotherapy resistance, and GSN expression levels in gynecological and head and neck cancers tissues are positively correlated with in vitro and in vivo chemical resistance." (PMID 37035750, 2023). "According to Wang (2014), head and neck cancer cell lines with higher endogenous gelsolin expression were more cisplatin resistant than those with lower gelsolin expression." (PMID 34144901, 2022). "In the literature, only two articles have reported the effect of gelsolin on head and neck cancers." (PMID 34144901, 2022). "Notably, Wang and colleagues in 2014 reported that GSN may regulate the sensitivity to chemotherapy in patients with head-and-neck cancer, whereas more recently Zhao and colleagues have reported the GSN involvement in radio-resistant LC patients." (PMID 30925779, 2019).
Stroke (6 papers, 2011 to 2025). Sudden impairment of blood flow to a part of the brain due to occlusion or rupture of an artery to the brain. "Low plasma levels of gelsolin have been reported in various metabolic disorders, such as cardiovascular diseases and stroke, in both animal experiments and epidemiological studies." (PMID 37107219, 2023). "It correlates with long-term tracking of response and quality-adjusted life of stroke patients with their plasma gelsolin levels." (PMID 31002695, 2019). "In stroke patients also, plasma gelsolin (pGSN) levels have been reported to decline significantly and a negative correlation with pGSN level was observed with the National Institute of Health Stroke Score/Scale (NIHSS) and C-reactive protein levels." (PMID 31002695, 2019). "Some of the stroke subtype-specific proteins (FBLN1, F2, SERPINF2, CBP2, FCN3, GPX3, IKG, and GSN) were also affected by the CBS deficiency." (PMID 31242583, 2019). "More relevant to our work, administration of recombinant gelsolin has been shown to have a protective effect in murine stroke." (PMID 31002695, 2019). "Increasing gelsolin levels during stroke may serve to modulate the inflammatory response thereby offering protection against the inflammation related neurodegeneration following stroke." (PMID 22047744, 2011). "Gelsolin-overexpressing transgenic mice demonstrate neuroprotection against experimental stroke, but it is not known whether these effects are mediated by pGSN or cGSN, or whether it is GSN near the infarct that mediates the protection." (PMID 22047744, 2011).
systemic amyloidosis (6 papers, 2014 to 2025). "For example, screening for systemic amyloidosis in patients with gelsolin mutation, as well as cardiac and respiratory disease in patients with mutations in MYH7, DMD and LAMA2 genes." (PMID 34103343, 2021). "Mutations in gelsolin are responsible for a systemic amyloidosis first described in 1969." (PMID 27633054, 2016). "Hereditary systemic amyloidosis is associated with mutations in transthyretin (ATTRv), fibrinogen (AFib), apolipoproteins (ApoAI, ApoAII, ApoC-II, ApoC-III), gelsolin (AGel), and lysozyme (ALys)." (PMID 40151750, 2025).
corneal dystrophy (5 papers, 2011 to 2023). The term corneal dystrophy embraces a heterogeneous group of bilateral genetically determined non-inflammatory corneal diseases that are usually restricted to the cornea. "By creating a disease map across various ocular tissues, they also demonstrated that gelsolin (GSN) mutations are significantly associated with corneal dystrophies." (PMID 37138096, 2023). "It gave an idea of how mutations of GSN could cause corneal dystrophy." (PMID 34584087, 2021).
invasive breast carcinoma (5 papers, 2015 to 2024). A carcinoma that infiltrates the breast parenchyma. "GSN deficiency increases with progression from atypical ductal hyperplasia (ADH) to ductal carcinoma in situ (DCIS) to invasive breast cancer (IBC)." (PMID 37834160, 2023). "According to research, the GSN protein was found to be deficient in 71% of human sporadic, invasive breast carcinomas and 56% of ductal carcinomas in situ." (PMID 35205837, 2022). "Studies have shown that 71 % of human sporadic, invasive breast carcinomas and 56 % of ductal carcinomas in situ were strikingly deficient in the GSN protein." (PMID 26482896, 2015). "The downregulation of gelsolin was also described by Winston and colleagues (2001) in invasive mammary carcinomas." (PMID 39061201, 2024).
leukemia (5 papers, 2019 to 2024). A malignant (clonal) hematologic disorder, involving hematopoietic stem cells and characterized by the presence of primitive or atypical myeloid or lymphoid cells in the bone marrow and the blood. "In leukemia U937 cells, gelsolin overexpression induced a retarded growth, an improved monocytic morphology, increased NADPH activity and enhanced superficial expression of the CD11b β-integrin receptor in comparison with U937 parental cells." (PMID 31437251, 2019). "Similar effects of gelsolin have previously been reported for non-voltage-gated sodium channels in leukemia cells." (PMID 38666184, 2023).
osteoporosis (5 papers, 2017 to 2026). A condition of reduced bone mass, with decreased cortical thickness and a decrease in the number and size of the trabeculae of cancellous bone (but normal chemical composition), resulting in increased fracture incidence. "Gelsolin (GSN) protein, expressed in circulating monocytes, was previously reported to be associated with osteoporosis in both Chinese and Caucasian women." (PMID 29787615, 2018). "Previous studies from our group have supported the contribution of GPD2, TPM4 and GSN to osteoporosis risk." (PMID 27878450, 2017). "Some of these proteins include Vitamin D Binding Protein (VDBP), ceruloplasmin (CP), and gelsolin (GSN), one of the proteins most frequently reported in patients with osteoporosis." (PMID 39062769, 2024). "Additionally, LTA has also shown potential in attenuating osteoporosis by inhibiting osteoclast differentiation through interference with gelsolin-actin dissociation." (PMID 41539856, 2026). "Overall, GSN is the main protein pointed out as a potential biomarker for osteoporosis." (PMID 39062769, 2024). "Among the identified proteins showing significant changes in expression between NOR, OS, and OP samples, serum levels of CP, GSN, NADPH 1, and SERPINC 1 were usually lower in osteopenia than in the osteoporosis group." (PMID 31766436, 2019).